SOD2 (superoxide dismutase 2)
Diseases named in the same sentence as SOD2 in open-access papers (continued):
Sharing a sentence is not in itself a finding about the gene and the disease.
cancer (continued). "The knockdown of SOD2-dependent ROS generation up-regulates HIF-1α expression in carcinoma cells." (PMID 33202982, 2020). "SOD2 overexpression correlates with poor prognosis in several cancers." (PMID 30700285, 2019). "The dynamic nature of RNA editing might play a role in the temporal regulation of SOD2 during cancer development, although further investigation is needed." (PMID 31870275, 2019). "Interestingly, we also observed that sorafenib can downregulate SOD-2 in cancer cells, and it is markedly prevented following c-Met activation." (PMID 30647407, 2019). "However, when evaluating the patient data, it is important to note that several studies have suggested a role for SOD2 in the promotion of cancer cell migration and invasion." (PMID 29478325, 2019). "First, the high SOD2 expression of cancer cells is a poor prognostic factor for EAOC." (PMID 30700285, 2019). "Thus, GPX1, SELENBP1, SELENON, SELENOK, and SOD2 were differently expressed only in the cancer tissues." (PMID 30469315, 2018). "SOD1 overexpression is frequently observed in many cancers, whereas SOD2 is downregulated." (PMID 30279365, 2018). "Among SOD family members, manganese superoxide dismutase 2 (MnSOD‐SOD2) plays an essential role not only in cancer but also in a wide range of stress‐induced diseases due to its localization in the mitochondria, where the production of ROS is higher compared to the other cellular compartments." (PMID 30259659, 2018). "Gastric cancer-associated lncRNA 1 (GClnc1) is a molecular bridge that connects specific enzyme complexes, e.g., histone methyltransferase (WDR5) and acetyltransferase (KAT2A), with the target gene SOD2." (PMID 29736267, 2018). "Therefore, there is likely a dichotomy where SOD2 can be considered a protective antioxidant reducing superoxide, as well as a pro-oxidant factor during cancer progression, with these effects depending on the accumulation and detoxification of H2O2." (PMID 29774090, 2018). "A recent review on SOD2 and carcinogenesis summarized that ROS largely originating in the mitochondria play essential roles in the metabolic and (epi) genetic reprogramming of cancer cell evolution towards more aggressive phenotypes." (PMID 29774090, 2018). "The role of SOD2 in cancer initiation and progression is not well understood." (PMID 29774090, 2018). "MiR-509-5p mimics, therefore, could disrupt the TrkAIII/SOD2 mitochondrial protection axis to facilitate cancer drug-induced mitochondrial ROS-mediated death." (PMID 29914559, 2018). "Reduction of oxidative stress by increasing SOD2 levels might prevent DNA injury and consequently cancer development." (PMID 29774090, 2018). "Additionally, considering the suggested cancer-related bivalence of SOD2, we also probed for probable epigenetic undertone to SOD2-associated phenotype and likely SOD2-attenuating 4-AAQB therapeutic activity in CRC." (PMID 30103475, 2018). "While much is known about the transcriptional regulation of the SOD2 gene, including downregulation by epigenetics and activation by stress response transcription factors, further research is required to understand the post-translational modifications that regulate SOD2 activity in cancer cells." (PMID 29099803, 2017). "Thus, further investigations need to be carried out to identify SOD2-specific kinases and phosphatases, SOD2 phosphorylation sites and the corresponding signaling pathways that regulate SOD2 phosphorylation in cancer." (PMID 29099803, 2017). "However, there are also examples where dampening of these pathways leads to SOD2 repression in cancer." (PMID 29099803, 2017). "siRNA-mediated silencing of the ABCB7 transporter in HeLa cells resulted in mitochondrial accretion of iron and SOD2 inactivation, suggesting that an altered Fe/Mn ratio in cancer cells could play a role in SOD2 activity regulation." (PMID 29099803, 2017). "Thus, further investigation needs to be carried out to unfurl the existence and function of nitrated SOD2 in cancer." (PMID 29099803, 2017).
cancer (continued). "High expression of several miRNAs has been correlated with low SOD2 expression in cancer." (PMID 29099803, 2017). "However, unlike SOD2 transcription, less is known about the regulation of SOD2 activity by these modifications in cancer." (PMID 29099803, 2017). "Another intriguing finding was the predominant negative effect of certain SOD2 alleles (rs4880-T, rs5746136-A, and rs8031-T) on concentration performance within our study sample regardless of cancer diagnosis or prescribed treatment group." (PMID 27099827, 2016). "The role of SOD2 in the context of cancer is still controversial." (PMID 27023612, 2016). "Previous studies have shown that SOD2, a well-known antioxidant enzyme, could play a part in the promotion or progression of certain cancers." (PMID 25402510, 2015). "As a consequence the role of SOD2 in cancer is complex and multifactorial." (PMID 25745358, 2015). "Studies have lacked information on other cancer-directed therapies, such as radiation therapy, whose effectiveness has been shown to be modified by SOD2 polymorphisms." (PMID 24498107, 2014). "In addition to understanding the relative mechanisms of SOD2 expression levels in cancer cells, little is known about the consequences of reduced SOD2 on the signal transduction and transcriptional processes that control cancer cell viability and growth." (PMID 17895890, 2007). "While our data show that SOD2-mediated proteasomal degradation plays a crucial role in promoting cancer cell fitness upon amino acid starvation, we next wondered whether this pathway also promotes survival in non-cancer cells." (PMID 40131931, 2025). "Moreover, in cancer progression, SOD2 has a dichotomous role." (PMID 39125641, 2024). "Therefore, SOD2 has dichotomous anti-tumourous and tumourigenesis effects in cancer." (PMID 37469404, 2023). "However, the role of SOD2 in cancer is complex, as it presents a dichotomy." (PMID 37108069, 2023). "Furthermore, SOD2 acetylation promoted cancer progression in mice." (PMID 37759978, 2023). "Additionally, Pro restrained cancer cell advancement via modulating circ-ZFR/miR-212-5p/SOD2 axis." (PMID 35543376, 2022). "Thus, meta-analysis on 15,320 cancer cases and 19,534 controls from 34 published case-control studies demonstrated no significant overall main effect of SOD2 rs4880 polymorphism on cancer risk." (PMID 31382611, 2019). "Hence, based on these data, SOD2 may represent a potential target for combination cancer therapy treatments." (PMID 29478325, 2019). "The down regulation of SOD2 may help promote the cancer progression." (PMID 30367578, 2018). "Therefore, the modulation in the ratio of SOD1/SOD2 may be a promising strategy for treating cancer cells." (PMID 30279365, 2018). "Since SOD2 can be regulated at the protein level by several post-translational modifications, there is the potential that its activity may be further regulated in the context of cancer." (PMID 29099803, 2017). "Therefore, gene therapy targeting SOD2 has potential in cancer radiotherapy." (PMID 27999194, 2017). "To further characterize the liquid-plasma-induced death of cancer cells via ROS or RNS, we determined whether a knockdown or overexpression of the enzymes scavenging reactive species (SOD1/SOD2 and catalase) influenced the liquid-plasma-induced death of cancer cells." (PMID 27364630, 2016). "In addition, a study using luciferase reporter assay revealed that miR-222 could bind the sod2 3′UTR, and the expression of SOD2 was reduced in a carcinoma cells when transfected with ectopic miR-222." (PMID 23935993, 2013). "This highlights how cancer cells exploit redox modulation of RTK signaling as a survival mechanism, presenting potential therapeutic targets in the NRF2-GPX4/SOD2 axis." (PMID 41009046, 2025).
cancer (continued). "To mitigate this, we focused on assessing mRNA levels of key antioxidant enzymes (NFE2L2, HMOX1, SOD2, CAT) in both thyroid normal and cancer cells to gain insight into their oxidative stress response ability." (PMID 40927570, 2025). "Concluding, our results confirmed that oxidative stress, especially NOS2 polymorphisms and changes in the expression and methylation of the promoters of SOD2 and NOS2 are involved in the cancer transformation initiation of the cell urinary bladder." (PMID 37660159, 2023). "Studies of SOD1, SOD2, or SOD3 in colorectal, lung, and other cancers have also been widely reported." (PMID 37759978, 2023). "Our results indicated NOTCH1, NOTCH3, FLCN, SOD1, SOD2, NF1, and TLR4 as upregulated proteins in different cancer types highlighting their role in cancer progression." (PMID 35001007, 2022). "IL-6 was previously reported to induce the expressions of COX-2 34, 35, MMP-9 36, Oct3/4 37, SOD2 38, 39 and CAT 39 in cancer cells." (PMID 33854627, 2021). "Enhanced cancer cell growth and migration are regulated by the activation of JAK2/STAT3 signaling and activated STAT3 further promotes circ-SOD2 expression through a positive feedback loop." (PMID 34205978, 2021). "There was variation in expression of SOD2, PRDX1 and GSR that didn’t correlate across the cancer cell lines and fibroblast." (PMID 33669867, 2021). "In order to corroborate with the expression of SOD2 in PCa tissues, we utilized IHS to test its expression among cancer subjects in our centers." (PMID 31929112, 2020). "Invasive abilities of cancer cells are related to migration and many other factors, including expressions of MMP-2, MMP-9, Rac1, Rho A, and SOD2." (PMID 31772330, 2020). "The comparison of the average SOD1, SOD2, and SOD3 mRNA synthesis in normal and PTC showed 4.6% (SD 4.9), 3.5% (SD 17.1), and 18.6% (SD 13.1) decreased expression in cancer, respectively." (PMID 29478325, 2019). "ALDH1A1-induced upregulation of SOD2 and GPX4, as well as ALDH1A1 itself, mitigates erlotinib-induced oxidative and carbonyl stress in cancer cells and imparts erlotinib resistance." (PMID 31695757, 2019). "Similar to SOD2, early studies have suggested that SOD3 is a tumor suppressor gene downregulated in cancer." (PMID 29478325, 2019). "NADPH NOX1 and especially SOD2 have been shown to stimulate MMP expression and to interrupt focal adhesions as part of the migration/invasion process in cancer progression." (PMID 29478325, 2019). "Several antioxidant proteins are up-regulated in chemoresistance such as SOD1, SOD2, and SOD3 in oxaliplatin-resistant cancer cells or SOD1 and Prx1 in 5-FU chemoresistance." (PMID 31658599, 2019). "Additional genes in this study, showing changes in gene expression for both the Irish and the Czech cancers were GPX2, GPX3, SELENOK, SEPHS2, SELENBP1, and SOD2." (PMID 30469315, 2018). "In contrast, SOD2 and GSTP1 are downregulated in the cancer cell lines secretome, according to the proteomic analysis." (PMID 28261610, 2017). "We examined the mechanism of SOD-2 upregulation as well as its role in EMT and migration of cancer cells." (PMID 28801561, 2017). "Out of the two main SOD isoforms, SOD1 and SOD2, the level of SOD1 is found to be more critical in ROS mediated cancer progression." (PMID 26682000, 2016). "SOD2, which has response elements for NF-κB, wipes out the superoxide anion radicals generated by OXPHOS and coverts them into hydrogen peroxide in cancer cells." (PMID 27551267, 2016). "Patients, who showed higher SOD2 expression level in the RCC samples, clearly include cancer cells with higher SOD2 expression." (PMID 27157976, 2016).
cancer (continued). "Since in absence of SOD2, superoxide levels are elevated and may cause irreversible damage, mechanisms must exist to retain superoxide below a critical threshold and maintain viability of cancer cells." (PMID 24955214, 2014). "Among the enzymes produced by cells that manage ROS, manganese superoxide dismutase (SOD2), the form of SOD found in mitochondria, has received considerable attention with regard to cancer." (PMID 17895890, 2007). "Moreover, Dyrk1B up-regulates the expression of several antioxidant genes, e.g., superoxide dismutases 2 and 3 (SOD2, SOD3) and ferroxidase in cancer cell lines." (PMID 38675189, 2024). "Activation of NRF2 axis in cancer cells triggers the induction of multiple anti-ferroptotic genes, including SLC7A11, ATP binding cassette subfamily C member 5 (ABCC5), metallothionein 1G (MT1G), FSP1, CBS, and superoxide dismutase 2 (SOD2)." (PMID 39624080, 2024). "New SOD-2 mimetics have been developed to reduce OS after radiotherapy in cancer patients, Avasopasem Manganese (GC4419 AVA), selectively reduces superoxide dismutase and peroxide in cancer patients." (PMID 39334797, 2024). "Due to the absence of apoprotein, the higher expression of SOD2 can be therefore considered as a response to the oxidative stress leading to alteration of the metabolic activity of cancer tissue." (PMID 37968795, 2024). "On the other hand, a relative decrease of the amount of hydrogen peroxide due to reduced activity of SOD2 will leave the cell without the stimulus for apoptosis, enabling it to survive and continue with the cascade of transformation into a cancer cell." (PMID 36676755, 2023). "Several mitochondria-related genes were differentially expressed between parental and resistant GBM cells, and among them, the superoxide dismutase 2 (SOD2) gene substantially affected various factors, including cancer stemness, treatment resistance, and patient survival." (PMID 37175412, 2023). "Western blotting results revealed that TMZ-resistant U87MG-R cells highly expressed CYBB along with Nrf2, SOD2, and other epithelial–mesenchymal transition (EMT) markers, such as slug, vimentin, N-Cadherin, and CD44, in addition to the upregulation of cancer stemness marker CD133." (PMID 37175412, 2023). "Moreover, the upregulated expression of SOD2, IL1B, PLAUR, CXCL3, and CCL20 promoting cancer cell invasion in other tumors depended on the NF-κB mechanism." (PMID 37954130, 2023). "SOD2 protects against ROS, while increased COX-2 levels were found to be the reason for enhanced cellular proliferation and apoptosis resistance in various cancers." (PMID 38140127, 2023). "Given the previous reports that SOD2 confers radioresistance to NPC cells, and that ferroptosis plays a key role in sensitizing cancer cells to IR, we carried out a colony formation assay in the presence of DFO, a ferroptosis inhibitor using SOD2 depleted and control NPC cells." (PMID 36737723, 2023). "The proteomic screening of cancer cells treated with OA has revealed that it downregulates several factors, such as mitochondrial uncoupling protein 2 (UCP2), MMP-2, MMP-9, PKM2, superoxide dismutase 2 (SOD2), hypoxia inducible factor 1 alpha (HIF-1α), and PROX1." (PMID 36139025, 2022). "While additional experiments such as downregulating SOD2 should be performed, these findings suggest that the efficiency of AXT as a treatment to enhance anti-cancer drug results might be affected by SOD2 expression in patients." (PMID 35204257, 2022). "However, there was noticeably lower baseline GSH in PC3 compared to the other PCa cells (LNCaP, C42B, RM1) and, additionally, PC3 express more SOD2, a primary generator of H2O2 which has also been shown to promote metastasis in other cancers." (PMID 35604506, 2022).
cancer (continued). "Overexpression of miR-146a, a micro-RNA dysregulated in many cancers, in epithelial ovarian cancer (EOC) downregulates SOD2 expression considerably, which consequently elevates ROS levels and leads to suppression of cell proliferation, promotion of apoptosis and enhancement of chemosensitivity." (PMID 36233276, 2022). "This way, the inhibitory effect of SOCS3 on JAK2 is annulled, and the subsequent activation of JAK2/STAT3 signaling enhances cancer cell growth and migration; interestingly, activated STAT3 binds to the promoter of circ-SOD2 and further promotes its expression through a positive feedback loop." (PMID 34205978, 2021). "Concentrations for treatment with antioxidants differ from study to study, and there has been no consistent conclusion on the effect of SOD2 on cancer." (PMID 33535682, 2021). "Upregulation of SOD2 could favor H2O2 accumulation, which is involved in a variety of signaling pathways related to proliferation, migration, and invasion in cancer cells." (PMID 33821873, 2021). "When cholangiocyte cell lines were treated with hydrogen peroxide for a long-term, they increased cancer cell properties such as high expression levels of antioxidant enzymes (e.g., catalase (CAT), superoxide dismutase-2 (SOD2)) and high cell proliferation rates compared to the parental cells." (PMID 33854627, 2021). "Intensification of SOD2 expression in tumoral cells seems to ensure H2O2 flow from mitochondria, which is a crucial step for the occurrence of the Warburg effect, a strategy used by cancer cells to increase the generation of additional metabolites." (PMID 33821873, 2021). "In addition, the survival analysis emphasized the prognostic significance of TRAFD1, SOD2, RIPK2, RBCK1, and MT2A as cancer-promoting factors in ccRCC and pRCC." (PMID 34795663, 2021). "MnSOD (SOD2) is shown to be frequently dysregulated in several cancers, and thus, there is an emerging interest in complexes that mimic MnSOD (MnSOD mimetics) as therapeutic agents against cancers with suppressed MnSOD activity." (PMID 34777681, 2021). "SOD2 and GSTM1 are responsible for the detoxification of reactive oxygen species (ROS) and electrophilic compounds, which are produced mainly by mitochondria in cancer cells." (PMID 32717915, 2020). "In cancer cells, similarly to the reduction of ATP production, the decrease of mitochondrial ROS formation is also significant, in which SIRT3 has been proved to play a pivotal role by the deacetylation and activation of superoxide dismutase 2 (SOD2) enzyme." (PMID 32117717, 2020). "Resveratrol-induced SOD2 expression was observed in cancer cells, although the expression of SOD1, CAT and GPX1 was not affected." (PMID 32316674, 2020). "Consequently, the levels of ROS, SOD2, CAT, and SULTs would be a group of closely related parameters to predict the therapeutic outcomes of resveratrol-based cancer therapy." (PMID 30116486, 2018). "TNF-α may be the major contributor of SOD-2 upregulation as well as EMT and migration in cancer cells." (PMID 28801561, 2017). "The binding of these can be influenced by other transcription factors that may be altered in cancer to either negatively or positively regulate the SOD2 promoter, damaged DNA binding 2 (DDB2) being an example of negatively influencing SOD2 basal transcription." (PMID 29099803, 2017). "Even though large-scale patient expression datasets, like The Cancer Genome Atlas (TCGA), give us important insights into the expression changes of SOD2 in different cancer types, these do not necessarily directly reflect on the activity of the enzyme." (PMID 29099803, 2017).